MIR4679-2 (microRNA 4679-2)
Synonyms: hsa-mir-4679-2
Gene: MicroRNA gene on chromosome 10 (89,063,335 to 89,063,411, reverse strand). Ensembl gene ENSG00000265375.
Homologues: Orthologues: chimpanzee MIR4679-2 (100% identical).